BHLHE40 (basic helix-loop-helix family member e40)
Diseases named in the same sentence as BHLHE40 in open-access papers (continued):
Sharing a sentence is not in itself a finding about the gene and the disease.
cancer (continued). "Because BHLHE40 and SREBF1 play important roles in apoptosis in other cancer cells, we examined whether BHLHE40 or SREBF1 knockdown could increase apoptosis in PCa cells." (PMID 38064101, 2024). "BHLHE40 is known to be involved in multiple types of cellular activity including apoptosis, senescence, cell cycle, multidrug resistance, and epithelial-to-mesenchymal transition in cancer cells." (PMID 38301894, 2024). "Bhlhe40 mediates the promotion or suppression of tumors depending on the cancer type." (PMID 39062912, 2024). "Although the EB model allowed us to address Bhlhe40’s role in regulating physiological vascularization, it would be interesting to study its contribution to pathological angiogenesis, such as, for example, in the context of cancer." (PMID 39062912, 2024). "Because AMPK is a central regulator of energy metabolism in cancer cells, targeting the BHLHE40‒PPM1F‒AMPK axis may represent a strategy to control cancer development." (PMID 38301894, 2024). "Compared with other cancer types, the mRNA level of BHLHE40 was upregulated in PCa." (PMID 38064101, 2024). "Because AMPK acts as a central regulator of energy metabolism in cancer cells, targeting the BHLHE40‒PPM1F‒AMPK axis may represent a strategy to control cancer development." (PMID 38301894, 2024). "BHLHE40 is a helix-loop-helix-type transcription factor that plays a critical role in cell differentiation and proliferation, and in many studies, BHLHE40 has been closely associated with the regulation of the TIME and cancer progression." (PMID 37377917, 2023). "The first were tightly regulated, through MELK, BRCA2, KIF14, BUB1, and TOP2A, by five TFs (NFE2L3, RUNX1, RUNX2, BHLHE40, and the aging cancer-specific SOX11), two LncRNAs (ST7OT1 and CDKN2BAS), and four miRNAs (miR-21-5p, miR-363-3p, miR-873-5p, and miR-138-1-3p)." (PMID 37191407, 2023). "And BHLHE40 facilitates the invasion of cancer cell by interacting with SP1." (PMID 36463222, 2022). "The balance of BHLHE41 and BHLHE40 expression and their molecular interaction might influence their roles in cancer development." (PMID 34768959, 2021). "Regardless, these reports indicate that in collaboration with Notch, BHLHE40 promoted cancer." (PMID 32577154, 2020). "Thus, BHLHE40 is a multi-functional protein that mediates the promotion or suppression of cancer in a context dependent manner." (PMID 32577154, 2020). "In a retrospective study focusing on archived non-small-cell lung carcinoma (NSCLC) tissues, investigators found that in 118 patient samples, BHLHE40 expression is markedly reduced (30.5% positivity) in cancer samples when compared with adjacent normal lung tissues (89.8%)." (PMID 32577154, 2020). "Thus, BHLHE40 is a multi-functional gene that mediates the promotion or suppression of cancer in a context dependent manner." (PMID 32577154, 2020). "BHLHE40 can be expressed in both the nucleus and the cytoplasm, and its functional role in cancer may vary accordingly." (PMID 32577154, 2020). "Among these differential RNAs from TGF-β1-EVs treated HPASMCs, palladin and bHLHE40 (also called Dec1), which have been shown to promote a malignant pro-proliferative phenotype in cancer cells by promoting epithelial-to-mesenchymal transition, were further validated." (PMID 31703702, 2019). "This analysis, applied to primary cancers with and without c-met mutation, showed overexpression of the BHLHE40 and KDM4C only in the c-met-mutated PRCC tumors, as predicted by c-met-mutated embryoid bodies transcriptome." (PMID 31575031, 2019). "However, there are no reports on notable correlations between DNA methylation of BHLHE40 and cancer." (PMID 31384392, 2019).
cancer (continued). "However, the role of BHLHE40 in tumors remains controversial, and its mechanisms may vary in different types of cancer." (PMID 40046513, 2025). "However, little is known about energy regulation by BHLHE40 in cancer cells." (PMID 38301894, 2024). "In summary, these findings suggest that BHLHE40 is a highly effective biomarker for predicting prognosis in PDAC and holds great promise as a target for cancer therapy." (PMID 37377917, 2023). "The dedifferentiated phenotype relies on newly acquired dependencies on IRF2, BHLHE40, and ZNFX1, which represent rare pan-cancer dependencies." (PMID 37554444, 2023). "ANGPTL4, BHLHE40, and VEGF are considered as critical genes in cancer studies, which play pivotal roles in biological processes and are somehow regulated by HIF1α." (PMID 33602983, 2021). "The regulation of expression of multiple genes by BHLHE40 and BHLHE41 also has been reported to affect cancer development in apoptosis, epithelial mesenchymal transition, and hypoxic reaction." (PMID 34768959, 2021). "Compared with the adjacent normal tissues, the expression of NR1D1, DBP, and BHLHE40 was increased, while the expression of CRY1 and CLOCK was decreased in cancer tissues." (PMID 34977153, 2021). "Comparing BHLHE40 knockdown cells and controls, the overlapping genes between the group of DEGs in the mRNA‐seq and that of genes with hypo‐accessible regions in ATAC‐seq were enriched in cancer‐related pathways and the regulation of lipid metabolic processes." (PMID 38064101, 2024). "Comparing the expression levels of genes in BHLHE40 KD SAL-treated samples with those of their paired controls revealed a reduction in the ‘cellular senescence’, an induction in the ‘PI3K/AKT signaling in cancer’, and a reduction in the ‘circadian clock’ pathways." (PMID 38902772, 2024). "Some factors identified (e.g., NF-κB, STAT3, FOS) are known to be involved for transformation in our model, others (e.g., CEBPB, HIF1a, ETS2, FHL2, TCF7L2, and NFE2L2) have been described as oncogenes in other settings, and some proteins (BHLHE40 and MAFB) have not been well linked to cancer." (PMID 29802342, 2018). "Hence, here we will focus on non-circadian aspects of BHLHE40 cellular function in cancer." (PMID 32577154, 2020). "Despite such limitations, our data demonstrated that circulating BHLHE40 and DDIT4 were differentially expressed in patients with HCC compared to individuals without cancer." (PMID 34045534, 2021). "Several of the direct FOXP1 targets upregulated in response to cancer were transcriptional repressors of the circadian clock, including Kfl9, Nr1d1, Per1, and Bhlhe40, providing further evidence that FOXP1 is a negative regulator of clock function in skeletal muscle in response to cancer." (PMID 40349340, 2025).
infection (10 papers, 2018 to 2025). The state of being infected such as from the introduction of a foreign agent such as serum, vaccine, antigenic substance or organism. "Using the mouse model of Chlamydia muridarum intravaginal infection, we showed that loss of Bhlhe40, either in the germline or specifically in T cells, resulted in higher bacterial shedding and significant delay in Chlamydia clearance from the FRT." (PMID 38271477, 2024). "In an M. tuberculosis infection model, loss of Bhlhe40 expression, specifically in CD11c+ cells, resulted in susceptibility of these mice to this infection, similar to what occurs in the Bhlhe40fl/fl-Cd4-cre mice." (PMID 37843306, 2023). "Furthermore, other infection models have shown that loss of Bhlhe40, specifically in CD4+ T cells, results in pronounced disease." (PMID 37843306, 2023). "STRA13, also known as BHLHE40 has been reported as a key regulator in immunity during infection, autoimmunity, and inflammatory." (PMID 39949782, 2025). "BHLHE40 is increasingly recognized as a key regulator of immunity in infection, autoimmunity, and inflammation, acting as a critical checkpoint between progenitor and effector T cell subsets." (PMID 41035636, 2025). "WT and Bhlhe40-/- mice were treated with either anti-IL-10R or isotype control antibody starting 1 day prior to C. muridarum intravaginal infection." (PMID 38271477, 2024). "In contrast, Bhlhe40-/- mice exhibited persistent high bacterial shedding from the FRT during the first 3 weeks of infection." (PMID 38271477, 2024). "Nevertheless, a role for Bhlhe40 appears to be context dependent, as in other intracellular infection models such as Listeria monocytogenes, Bhlhe40 is largely dispensable for host resistance." (PMID 38271477, 2024). "CD4 T cell polyfunctionality index was lowest in Bhlhe40-/- mice and highest in Il10-/- mice, and these indices reversely correlated with bacterial shedding over the course of C. muridarum primary infection." (PMID 38271477, 2024). "We therefore measured CD4 T cell cytokine production in WT and Bhlhe40-/- mice at day 14 post C. muridarum intravaginal infection." (PMID 38271477, 2024). "Lastly, Bhlhe40 deletion in T cells resulted in a phenotype similar to that observed in the Bhlhe40−/− mice, indicating that Bhlhe40 expression in T cells contributes to the ability of mice to control infection with P. yoelii." (PMID 37843306, 2023). "By day 7 p.i., the quantity of IL-10 in the serum was significantly elevated in the Bhlhe40−/− mice, suggesting an early role for Bhlhe40 in suppressing IL-10 expression after infection." (PMID 37843306, 2023). "Transcripts for Bhlhe40 were present in the spleen of naïve WT mice and after infection, with a significant increase in expression seen at day 5 p.i.." (PMID 37843306, 2023). "Here, leukocytes, specifically CD4+ T cells, upregulate Bhlhe40 expression in the spleen and liver in response to infection with P. yoelii." (PMID 37843306, 2023). "Since Bhlhe40 was expressed during infection, the ability of Bhlhe40−/− mice to control a P. yoelii infection was monitored." (PMID 37843306, 2023). "The factor BHLHE40 has emerged as an important regulator of immunity during infection, autoimmunity, and inflammatory conditions, especially in cytokine production and proliferation." (PMID 37026010, 2023). "The findings here indicate that Bhlhe40−/− mice infected with P. yoelii exhibit an intact B-cell response, as robust Tfh and GC B-cell populations were observed in Bhlhe40−/− mice throughout the infection." (PMID 37843306, 2023). "The data presented here demonstrate that the transcriptional regulator Bhlhe40 plays a critical role in supporting the control and clearance of infection with P. yoelii in mice." (PMID 37843306, 2023). "Findings here demonstrate that Bhlhe40 plays an essential role in controlling infection with P. yoelii in mice by repressing IL-10 expression in T cells." (PMID 37843306, 2023).
infection (continued). "Furthermore, the early plasmablast response and parasite-specific Ab titers and Ab affinity maturation were also comparable between Bhlhe40−/− and WT mice, which likely explains the ability of the Bhlhe40−/− mice to control their infection eventually." (PMID 37843306, 2023). "One viable cell population that might also require Bhlhe40 expression for infection control is CD11c+ cells." (PMID 37843306, 2023). "The rapid decline in Bhlhe40 transcripts in the spleen after infection suggests a transient expression of this gene after T-cell activation, which may be accompanied by a rapid turnover of the transcription factor." (PMID 37843306, 2023). "While data implicating a role for Bhlhe40 expression in activated macrophages are limited, there is evidence that inflammatory signals can induce Bhlhe40 expression in these cells, suggesting a role for Bhlhe40 in regulating gene expression in macrophages after infection." (PMID 37843306, 2023). "Infection with Lenti-B40, a recombinant lentivirus encoding BHLHE40, raised the level of BHLHE40 mRNA in the absence of insulin and prevented the rapamycin-mediated reduction of BHLHE40 mRNA in the presence of insulin." (PMID 29952285, 2018). "In addition, long-term FRT tissue pathology was not affected by Bhlhe40 deficiency, as WT and Bhlhe40-/- mice had similar pathology scores in uterine horns and oviducts at 140–150 days post infection (dpi)." (PMID 38271477, 2024). "However, in response to infection with intracellular pathogens, Bhlhe40 plays a protective role." (PMID 37843306, 2023). "Lastly, examination of cytokine production at later times after infection indicated that CD4+ T cells did not maintain their ability to produce IL-10 at a higher rate in the absence of Bhlhe40." (PMID 37843306, 2023). "Studies in these infection models showed that when Bhlhe40 is absent in CD4+ T cells, IL-10 production increases, while IFN-γ production decreases." (PMID 37843306, 2023). "The observation that Bhlhe40−/− CD4+ T cells exhibit a significant increase in IL-10 RNA and protein production suggests that Bhlhe40 acts during the early stages of a P. yoelii infection, to suppress IL-10 expression in CD4+ T cells, as it does in response to other Th1-centric infections." (PMID 37843306, 2023). "Many LCM-associated regulons were not altered by infection (C/EBPβ), while others were lost (RARG and MAF) and others gained (KLF4, STAT3, FOSB, and BHLHE40)." (PMID 36948193, 2023). "In the absence of insulin, infection with Lenti-B40 increased the BHLHE40 mRNA to levels similar to those seen after insulin treatment." (PMID 29952285, 2018). "To further expand our understanding of how Bhlhe40 regulates anti-Chlamydia immunity, we performed 5’ single-cell RNA sequencing (scRNAseq) and TCR profiling on activated CD4 T cells (CD44hi) sorted from WT and Bhlhe40-/- mouse FRT 14 days post intravaginal infection." (PMID 38271477, 2024). "Therefore, it was of interest to determine if Bhlhe40 plays a similar role in response to infection with non-lethal P. yoelii 17X." (PMID 37843306, 2023). "Overall, the data suggest that Bhlhe40 negatively regulates IL-10 production in the spleen after infection with P. yoelii and that splenic antigen-specific CD4+ T cells contribute to the elevated IL-10 production in the absence of Bhlhe40." (PMID 37843306, 2023).
cardiovascular diseases (1 paper, 2022). "Several studies reported that Bhlhe40 also plays a key role in cardiovascular diseases." (PMID 36304536, 2022).
BHLHE40 also shares sentences with these, for which no sentence is quoted: Alzheimer disease (2 papers); brain tumor (2); chronic kidney disease (2); clear cell carcinoma (2); liver cancer (2); sarcoma (2); acute kidney injury (1); acute myeloid leukemia (1); adenomyosis (1); anaplastic thyroid carcinoma (1); bipolar disorder (1); Cirrhosis (1); colon adenocarcinoma (1); congestive heart failure (1); depression (1); differentiated thyroid carcinoma (1); edema (1); encephalomyelitis (1); endothelial dysfunction (1); follicular thyroid carcinoma (1); Granuloma (1); head and neck cancer (1); HTLV infection (1); Hyperglycemia (1); hypothyroidism (1); immune system disease (1); infectious disease (1); inflammation (1); invasive breast carcinoma (1); keratoconus (1).
A further 31 diseases each share a sentence with BHLHE40 in 1 paper.